RN7SKP256 (RN7SK pseudogene 256)
Gene: Miscellaneous RNA gene on chromosome 6 (53,415,294 to 53,415,607, reverse strand). Ensembl gene ENSG00000253010.
Homologues: Orthologues: chimpanzee 7SK (95% identical). Paralogues in human: RN7SKP133 (54% identical), RN7SKP230 (52% identical), 7SK (51% identical), RN7SKP240 (51% identical), RN7SKP160 (51% identical), RN7SKP33 (51% identical), RN7SKP77 (51% identical), RN7SKP127 (50% identical), RN7SKP165 (50% identical), RN7SKP177 (50% identical), RN7SKP254 (50% identical), RN7SKP294 (50% identical), and 283 more.